MBOAT7 (membrane bound acylglycerophosphatidylinositol O-acyltransferase MBOAT7)
Description:
Acyltransferase which catalyzes the transfer of an acyl group from an acyl-CoA to a lysophosphatidylinositol (1-acylglycerophosphatidylinositol or LPI) leading to the production of a phosphatidylinositol (1,2-diacyl-sn-glycero-3-phosphoinositol or PI) and participates in the reacylation step of the phospholipid remodeling pathway also known as the Lands cycle. Prefers arachidonoyl-CoA as the acyl donor, thus contributing to the regulation of free levels arachidonic acid in cell. In liver, participates in the regulation of triglyceride metabolism through the phosphatidylinositol acyl-chain remodeling regulation.
Synonyms: LPIAT; BB1; LENG4; OACT7; hMBOA-7; LPLAT; LPIAT1; LPLAT11; LRC4; MBOA7; MRT57
Tractability: Antibody: UniProt predicts a signal peptide or a membrane-spanning region. PROTAC: ubiquitination databases record sites on it; its protein half-life has been measured.
Target class: Enzyme; Transferase
Gene: Protein-coding gene on chromosome 19 (54,173,412 to 54,189,882, reverse strand). Ensembl gene ENSG00000125505.
Subcellular location: Endoplasmic reticulum membrane
Subcellular location (Human Protein Atlas): Cytosol
Pathways (Reactome):
Metabolism: Acyl chain remodelling of PI
Gene Ontology:
Molecular function: acyltransferase activity, transferring groups other than amino-acyl groups; protein binding; 1-acylglycerol-3-phosphate O-acyltransferase activity; 2-acylglycerol-3-phosphate O-acyltransferase activity; lysophospholipid acyltransferase activity; 1-acylglycerophosphocholine O-acyltransferase activity
Biological process: phosphatidylcholine acyl-chain remodeling; phosphatidylinositol acyl-chain remodeling; phosphatidylinositol biosynthetic process; regulation of triglyceride metabolic process; layer formation in cerebral cortex; lipid modification; phospholipid metabolic process
Cellular component: endoplasmic reticulum; endoplasmic reticulum membrane; membrane; mitochondria-associated endoplasmic reticulum membrane contact site
Genetic constraint (gnomAD): Loss-of-function variants: 40 observed, 42.38 expected, observed/expected ratio (o/e) 0.94, 90% interval 0.73 to 1.23. The synonymous counts are far from expectation, so gnomAD's model fits this gene poorly and the ratio says little. Missense variants: 680 observed, 625.43 expected, observed/expected ratio (o/e) 1.09, 90% interval 1.02 to 1.16. Synonymous variants: 361 observed, 275.52 expected, observed/expected ratio (o/e) 1.31, 90% interval 1.2 to 1.43.
Gene-disease validity (ClinGen):
ClinGen rates the evidence that MBOAT7 causes each of these diseases.
complex neurodevelopmental disorder (autosomal recessive): Definitive. A disorder that involves more than one phenotype associated with the central nervous system, including but not limited to intellectual disability, autism, and seizures (epilepsy).
Homologues: Orthologues: chimpanzee MBOAT7 (99% identical), macaque MBOAT7 (99% identical), dog MBOAT7 (96% identical), pig MBOAT7 (96% identical), rat Mboat7 (94% identical), mouse Mboat7 (94% identical), guinea pig MBOAT7 (90% identical), tropical clawed frog mboat7 (61% identical), zebrafish mboat7 (56% identical), Drosophila melanogaster frj (28% identical), Caenorhabditis elegans mboa-7 (23% identical). Paralogues in human: MBOAT2 (25% identical), MBOAT1 (23% identical), LPCAT3 (20% identical), PORCN (17% identical), MBOAT4 (15% identical).
Diseases named in the same sentence as MBOAT7 in open-access papers:
MBOAT7 is named in the same sentence as 70 diseases in open-access papers, as found by Europe PMC text mining. Sharing a sentence is not in itself a finding about the gene and the disease. The quoted sentences say what the papers report.
Hepatic steatosis (40 papers, 2016 to 2026). Steatosis is a term used to denote lipid accumulation within hepatocytes. "Variation at APOE, MTARC1, and MBOAT7 has been found to confer risk of hepatic steatosis and cirrhosis." (PMID 40823170, 2025). "In parallel, four independent groups also showed that Mboat7 loss of function promotes hepatic steatosis, inflammation, and fibrosis in mice." (PMID 38648183, 2024). "The rs641738 C>T variant of MBOAT7 impairs lipid homeostasis by enhancing phosphatidylinositol turnover and promoting triglyceride synthesis, which consequently leads to liver steatosis and inflammation." (PMID 38504356, 2024). "Collectively, these data suggest that MBOAT7 has clear cell autonomous roles in regulating circulating and tissue LPI and PI pools and MBOAT7-driven LPI acylation in hepatocytes is the primary driver of hepatic steatosis seen with MBOAT7 loss-of-function." (PMID 36806709, 2023). "MBOAT7 mutations cause brain developmental disorders, and reduced expression is linked to fatty liver disease." (PMID 37316513, 2023). "Although not all human studies agree there is a uniform association between the rs641738 SNP with liver injury across all etiologies, all studies in mice confirm that Mboat7 loss of function in mice can promote hepatic steatosis and fibrosis." (PMID 35636492, 2022). "Recent studies in mice also show that Mboat7 loss of function can promote hepatic steatosis, inflammation, and fibrosis, causally linking this phosphatidylinositol remodeling enzyme to liver health in both rodents and humans." (PMID 35636492, 2022). "This work shows that SREBP-1c-driven de novo lipogenesis programs are in part necessary for the hepatic steatosis seen with MBOAT7 deficiency." (PMID 35636492, 2022). "The causative relationship of MBOAT7 with fatty liver has been experimentally confirmed by several in vitro and in vivo studies, showing that MBOAT7 loss leads to steatosis development, hepatic fibrosis and the formation of lipid droplets in hepatic cells." (PMID 35204498, 2022). "Much like the other Mboat7 loss-of-function studies, this work also saw striking hepatic steatosis in Mboat7HKO mice." (PMID 35636492, 2022). "In the past year, several lines of research have focused on unraveling the molecular mechanism(s) by which MBOAT7 deficiency induces hepatic steatosis." (PMID 33582144, 2021). "The causative role of MBOAT7 in fatty liver has been independently reported by Helsley and then by Tanaka." (PMID 34680476, 2021). "This study reveals a clear relationship between PI fatty acid composition and regulation of hepatic fat synthesis and delineates the mechanism by which mutations in MBOAT7 cause hepatic steatosis." (PMID 32859645, 2021). "To elucidate the link between these variants and fatty liver disease, we characterized Mboat7 liver-specific KO mice (Mboat7 LSKO)." (PMID 32859645, 2021). "Genetic variants that increase the risk of fatty liver disease and cirrhosis have recently been identified in the proximity of membrane-bound O-acyltransferase domain-containing 7 (MBOAT7)." (PMID 32859645, 2021). "In contrast to the striking hepatic steatosis seen with Mboat7 loss of function, Tmc4 null mice show similar levels of hepatic lipids when fed a high fat diet." (PMID 31621579, 2019). "Evidence indicates that the rs641738 mutation promotes development of fatty liver by abolishing MBOAT7’s enzymatic activity, as liver specific genetic knockdown in mice causes spontaneous steatosis within the liver, similar to human patients which express the rs641738 variant." (PMID 38247511, 2024). "We previously demonstrated that antisense oligonucleotide-mediated knockdown of Mboat7, the gene encoding membrane bound O-acyltransferase 7, in the liver and adipose tissue of mice promoted high fat diet-induced hepatic steatosis, hyperinsulinemia, and systemic insulin resistance." (PMID 36806709, 2023).
Hepatic steatosis (continued). "To determine whether inactivation of Mboat7 in the liver causes hepatic steatosis by increasing the rate of DNL, we examined the mRNA levels of genes encoding enzymes involved in fatty acid and sterol synthesis." (PMID 32859645, 2021). "We did this study to see whether one specific change (‘variant’) in one gene (‘MBOAT7’) was linked to fatty liver disease." (PMID 32882372, 2021). "MBOAT7 knockdown in the liver and adipose tissue of mice promoted hepatic steatosis and inflammation, hyperinsulinemia, and insulin resistance." (PMID 41019340, 2025). "It is interesting to note that mutations in PNPLA3, MBOAT7, and TM6SF2 are associated with fatty liver disease; however, TM6SF2 has a contrasting effect on CKD compared to mutations in PNPLA3 and MBOAT7." (PMID 38247511, 2024). "It was found that a variety of gene sites are related to the risk, disease severity, hepatic steatosis and advanced fibrosis of NAFLD, including PNPLA3, TM6SF2, GCKR, MBOAT7, APOC3, HSD17B13, etc.." (PMID 36973654, 2023). "Using an antisense oligonucleotide (ASO)-mediated approach, we recently showed that Mboat7 knockdown exacerbated high fat diet (HFD)-induced hepatic steatosis and inflammation, hyperinsulinemia, and insulin resistance." (PMID 36806709, 2023). "Mboat7HSKO mice have profound hepatic steatosis and elevated alanine aminotransferase, confirming the concept that MBOAT7 activity in hepatocytes opposes hepatic steatosis and liver injury." (PMID 36806709, 2023). "The most straightforward explanation is that either the substrates (LPIs or fatty acyl-CoAs) or products (38:3, 38:4, and 38:5 PI) of the MBOAT7 reaction initiate some signal in the liver to promote hepatic steatosis, inflammation, and fibrosis." (PMID 35636492, 2022). "Our data suggest a potential plausible link between fatty liver disease and COVID-19 severity mediated by the interaction of TLRs, MBOAT7, and MBOAT7 genotype." (PMID 36473860, 2022). "In this work, Mboat7 depletion induced hepatic steatosis by increasing de novo lipogenesis driven by the activation of sterol regulatory element–binding protein-1c (SREBP-1c), a key lipogenic transcription factor involved in fatty acid biosynthesis." (PMID 33582144, 2021). "The major finding of this study is that genetic ablation of Mboat7 in livers of mice results in hepatic steatosis and elevated liver function tests." (PMID 32859645, 2021). "Mboat7 ASO-driven hepatic steatosis was characterized by accumulation of triglycerides, free cholesterol, and cholesterol esters only in high fat fed cohorts." (PMID 31621579, 2019). "Studies in mice also found that Mboat7 ablation could promote hepatic steatosis, inflammation and fibrosis." (PMID 40760121, 2025). "Likewise, Mboat7-HSKO mice showed elevated hepatic steatosis scores and triglyceride levels under both pair-fed and ethanol-fed conditions." (PMID 38648183, 2024). "Here, we find that adipocyte Mboat7 contributes less so to hepatic steatosis and injury than hepatocyte Mboat7 but instead plays a critically important role in regulating local adipose tissue LPI/PI homeostasis, hyperinsulinemia, and systemic insulin sensitivity." (PMID 36806709, 2023). "Decreased VLDL secretion or aberrant insulin signaling did not cause hepatic steatosis in Mboat7 LSKO mice." (PMID 32859645, 2021). "The authors proposed a non-canonical pathway underpinning the association between MBOAT7 deficiency and hepatic steatosis." (PMID 33582144, 2021). "Mboat7 knockdown promotes hepatic steatosis and worsen liver injury." (PMID 31621579, 2019). "Membrane bound O-acyltransferase domain-containing 7 (MBOAT7) gene variant rs641738 C>T has been associated with liver steatosis development and severity, but not with insulin resistance." (PMID 31010049, 2019). "Importantly, Mboat7 ASO-driven hepatic steatosis was consistently seen with two distinct ASOs targeting different regions of the Mboat7 messenger RNA." (PMID 31621579, 2019).
Hepatic steatosis (continued). "The severity of hepatic steatosis is modulated by genetic variants, such as patatin-like phospholipase domain containing 3 (PNPLA3) rs738409, transmembrane 6 superfamily member 2 (TM6SF2) rs58542926, and membrane-bound O-acyltransferase domain containing 7 (MBOAT7) rs641738." (PMID 36555467, 2022). "Finally, the gene polymorphisms including TM6SF2/PNPLA3/MBOAT7 which are highly related to the abnormal metabolic disease and fatty liver disease are not evaluated in our study." (PMID 35186751, 2022). "Finally, we examined the possibility that MBOAT7 may be a determinate of metabolism locally at the surface of cytosolic lipid droplets to regulate hepatic steatosis, given that one recent study reported that MBOAT7 can localize to cytosolic lipid droplets." (PMID 31621579, 2019). "Moreover, genetic polymorphisms, such as Patatin-like phospholipase domain-containing protein 3 (PNPLA3), transmembrane 6 superfamily member 2 gene (TM6SF2) and membrane bound O-acyltransferase domain containing 7 gene (MBOAT7), are also associated with hepatic steatosis and fibrosis." (PMID 29874807, 2018). "Finally, we cannot exclude that other genetic variants, which had not been identified when we performed our study, eventually contribute to the risk of fatty liver disease in HIV infection, analogous to the recent addition of the MBOAT7 gene to the genetic risk factors in alcohol-related cirrhosis." (PMID 28594920, 2017). "The enzyme membrane-bound O-acyltransferase domain-containing 7 (MBOAT7) modulates this axis by acylation of LPI, exacerbating hepatic steatosis and insulin resistance." (PMID 41823054, 2026). "Genetic variations (PNPLA3, TM6SF2, GCKR, MBOAT7, MERTK, and HSD17B13) are one of the non-modifiable risk factors for metabolic dysfunction-associated fatty liver disease (MAFLD) and MASLD." (PMID 40507973, 2025). "In contrast, genetic deletion of Mboat7 in hepatocytes is sufficient to drive hepatic steatosis but does not drastically alter hyperinsulinemia or insulin sensitivity in either chow or HFD fed mice." (PMID 36806709, 2023). "In addition, the hepatocyte-specific depletion of both Mboat7 and SREBP cleavage–activating protein (Scap) normalized hepatic fat content similarly to Scap depletion alone, supporting that Mboat7-mediated hepatic steatosis was due to SREBP-1c processing." (PMID 33582144, 2021). "Unlike many other models of hepatic steatosis, there were no significant alterations in lipogenic gene expression either in the fed or fasted state with Mboat7 knockdown." (PMID 31621579, 2019). "Furthermore, MBOAT7 overexpression resulted in mild improvements in hepatic steatosis and markers of liver injury, but garnered no significant improvements in MAFLD pathology overall." (PMID 38247511, 2024). "Interestingly, adipocyte-specific deletion of Mboat7 also promotes mild hepatomegaly and hepatic steatosis after 20 weeks of HFD feeding but not shorter durations." (PMID 36806709, 2023). "More recently, several independent laboratories have shown that hepatocyte-specific deletion of Mboat7 (Mboat7HSKO) worsens hepatic steatosis, inflammation, and fibrosis, but unlike the oligonucleotide-based knockdown, does not impact insulin or glucose homeostasis." (PMID 36806709, 2023). "Given the fact that the rs641738 polymorphism is located in exon 1 of the TMC4 gene, and we unexpectedly found that Mboat7 ASO treatment also reduces Tmc4 expression, we wanted to examine whether alteration in Tmc4 may also be a key regulator of hepatic steatosis." (PMID 31621579, 2019). "Given that Mboat7 knockdown promoted striking hepatic steatosis, and the fact that adipose tissue expression of Mboat7 is negatively correlated with insulin sensitivity across strains of the HMDP we examined glucose homeostasis in Mboat7 ASO-treated mice fed a high fat diet." (PMID 31621579, 2019).
Hepatic steatosis (continued). "Our findings here with MBOAT7-driven restructuring of the lipid droplet surface, and those recently published with PNPLA3, suggest that alterations in lipid modifying enzyme access to the surface of cytosolic lipid droplets may be a common mechanism by which human fatty liver develops." (PMID 31621579, 2019). "Mboat7 ASO treatment promoted an increase in liver weight and striking hepatic steatosis in HFD-fed, but not chow-fed mice." (PMID 31621579, 2019).
liver disease (34 papers, 2016 to 2025). "The Mboat7 loss-of-function variant rs641738TT is associated with severe liver diseases in human, which is likely to occur through phosphatidylinositol (PI) remodeling." (PMID 40760121, 2025). "The convergent pathophysiology through lipid metabolism in MASLD and alcohol-associated liver disease has been further reinforced by the linkage of MBOAT7-rs641738 to both diseases, given that MBOAT7 encodes a membrane-bound lipid acyltransferase." (PMID 39774697, 2025). "Collectively, MBOAT7 is a genetic determinant of advanced liver disease, but how this gene shapes susceptibility to environmental cues is still an area of intense investigation." (PMID 38648183, 2024). "Recent genome-wide association studies (GWAS) have identified a link between single-nucleotide polymorphisms (SNPs) near the MBOAT7 gene and advanced liver diseases." (PMID 38648183, 2024). "Since 2015, several independent GWAS studies have identified a liver disease susceptibility locus (rs641738) near the genes encoding MBOAT7 and TMC4." (PMID 38648183, 2024). "The rs641738 inherited variant associated with reduced hepatic MBOAT7 expression has been linked to steatotic liver disease susceptibility." (PMID 37628684, 2023). "Loss-of-function mutations in human MBOAT7 result in liver disease, intellectual disability, early onset seizures, and autism spectrum disorders." (PMID 37316513, 2023). "The clear association between MBOAT7 loss-of-function and diverse liver diseases serves as yet another example of how genetics can powerfully identify new pathways relevant to human disease." (PMID 36806709, 2023). "Its rs641738C>T allele has been reported to be associated with fibrosis in a number of liver diseases, and it was recently shown that a loss of MBOAT7 leads to liver fibrosis, to which the mechanism is incompletely understood." (PMID 35579278, 2022). "An important advance has been made within the past several years, as several genome-wide association studies have discovered that an SNP near the gene encoding membrane-bound O-acyltransferase 7 (MBOAT7) is associated with severe liver diseases." (PMID 35636492, 2022). "Moving forward, we simply need a village of creative lipid scientists to identify the mechanism(s) by which MBOAT7 loss of function promotes human disease, with the long-term goal of developing new treatments for diverse liver diseases." (PMID 35636492, 2022). "This ASO approach allowed us to circumvent the postnatal lethality of global Mboat7 deletion and permitted the first reported investigation into high-fat diet-induced liver disease progression with near complete loss of function of Mboat7 in the liver." (PMID 35636492, 2022). "MBOAT7 expression has previously been associated with gastrointestinal cancer risk as well as lipid-linked liver diseases, which we were able to link to lipidome alterations by only considering the LINEX network." (PMID 34436429, 2021). "Increasing evidence indicates that the genetic variation of rs641738 in MBOAT7 increases the susceptibility risk to liver disease." (PMID 33335874, 2020). "Instead, selective loss of function of the neighboring gene Mboat7 is sufficient to sensitize mice to high fat diet-driven liver disease progression." (PMID 31621579, 2019). "Based on hepatic expression quantitative trait loci analysis, it has been suggested that MBOAT7 loss of function promotes liver disease progression, but this has never been formally tested." (PMID 31621579, 2019). "This ASO approach allows us to circumvent the postnatal lethality of global Mboat7 deletion, and permits investigation into obesity-linked liver disease progression with near complete loss of function of Mboat7 in the liver." (PMID 31621579, 2019). "Within the last two years, several independent GWAS studies have identified a liver disease susceptibility locus (rs641738) within a linkage-disequilibrium block that contains genes encoding MBOAT7 and TMC4." (PMID 31621579, 2019).